ENSG00000253059
Synonyms: LOC124900348
Gene: Small nucleolar RNA gene on chromosome 14 (35,756,327 to 35,756,463, forward strand). Ensembl gene ENSG00000253059.
Gene Ontology:
Biological process: RNA processing
Cellular component: nucleolus
Homologues: Paralogues in human: SNORA31B (85% identical), SNORA31 (65% identical).